GSTM1 (glutathione S-transferase mu 1)
Diseases named in the same sentence as GSTM1 in open-access papers (continued):
Sharing a sentence is not in itself a finding about the gene and the disease.
kidney failure (4 papers, 2019 to 2024). An acute or chronic condition that is characterized by the inability of the kidneys to adequately filter the blood. "Evidence from the Atherosclerosis Risk in Communities Study revealed a 66% increased risk of kidney failure in both Black and White individuals with GSTM1 inactive genotypes, compared with those with active genotypes." (PMID 35967115, 2022). "Some smaller case–control studies also tested a recessive genetic model (0 copies vs. 1 or 2 copies) of GSTM1 and found that GSTM1 0 copy was associated with kidney failure in several case–control studies." (PMID 31555322, 2019). "The association between GSTM1 copy number and kidney failure was reported in the Atherosclerosis Risk in Communities (ARIC) study, which had a larger sample size, both in blacks and whites." (PMID 31555322, 2019). "In fully adjusted models among whites in ARIC, loss of GSTM1 was associated with risk of kidney failure (0 or 1 copy vs. 2 copies: HR 2.54; 95% CI: 1.32–4.88)." (PMID 31555322, 2019). "Second, the sample size of blacks was small with only 796 patients available for analysis, limiting the power to examine an association between GSTM1 and kidney failure in this population." (PMID 31555322, 2019). "Data from the ARIC and AASK cohorts suggested that the loss of GSTM1 increased the risk of kidney failure or accelerated CKD progression." (PMID 31555322, 2019). "Confirming whether or not loss of GSTM1 increases the risk of kidney failure is important, given the high prevalence of GSTM1 loss in the population and the serious morbidity and mortality associated with kidney failure." (PMID 31555322, 2019). "Additional research is needed to confirm whether loss of GSTM1 increases risk of kidney failure in certain subgroups such as blacks." (PMID 31555322, 2019). "In this study, we examine the relationship between GSTM1 copy number and incident kidney failure in the Geisinger MyCode cohort." (PMID 31555322, 2019). "Characteristics of participants at baseline by GSTM1 copy number and follow-up kidney failure cases." (PMID 31555322, 2019). "There is evidence to suggest that the protective, antioxidant effects of GSTM1 are of greater importance in a uremic environment (i.e., at lower GFR), and this may account for the disparity between risk of incident CKD and kidney failure in this cohort." (PMID 35967115, 2022). "In conclusion, our study does not support an association between loss of GSTM1 and increased risk of kidney failure in whites." (PMID 31555322, 2019).
laryngeal carcinoma (4 papers, 2011 to 2022). Carcinoma that arises from the laryngeal epithelium. "In conclusion, this meta-analysis supported that the GSTM1 gene polymorphism was associated with laryngeal cancer, particularly in Caucasians." (PMID 22900055, 2012). "The combined results based on all studies showed that the GSTM1 null genotype was associated with increased laryngeal cancer risk (OR = 1.17, 95% CI = 1.04∼1.31)." (PMID 22900055, 2012). "The subgroup analysis based on source of controls also suggested that the GSTM1 null genotype was associated with laryngeal cancer risk in the population-based studies, which supported the association between GSTM1 polymorphism and laryngeal cancer risk." (PMID 22900055, 2012). "The aim of the present study was to conduct a meta-analysis assessing the possible associations of GSTM1 gene polymorphism with laryngeal cancer risk." (PMID 22900055, 2012). "The combined results based on all studies showed that GSTM1 null genotype was associated with increased laryngeal cancer risk (OR = 1.17, 95% CI = 1.04∼1.31)." (PMID 22900055, 2012). "Overall and subgroup analysis of GSTM1 and laryngeal cancer risk." (PMID 22900055, 2012). "This meta-analysis supported that the GSTM1 gene polymorphism was associated with laryngeal cancer, particularly in Caucasians, and these associations varied in different subgroup, which indicated that population-based study with larger sample size was more appropriate in design of future study." (PMID 22900055, 2012). "Hence, we undertook this meta-analysis, which supported that GSTM1 gene polymorphism was associated with laryngeal cancer and suggested that GSTM1 null genotype had an effect on the risk of developing laryngeal cancer among Caucasians." (PMID 22900055, 2012). "Therefore, we conducted this updated meta-analysis that might increase statistical power to address the possible associations of GSTM1 gene polymorphism with laryngeal cancer risk." (PMID 22900055, 2012). "This study is the first to investigate the polymorphisms of TERTRs2736100 and the GST supergene family (GSTM1, GSTT1) as potential risk factors for laryngeal cancer among smokers of northern Romanian descent." (PMID 36013573, 2022). "Concerning the GSTM1 null genotype in laryngeal cancer, two meta-analyses have been published before 2009, nevertheless, they had not reached unanimity in their conclusions." (PMID 22900055, 2012). "Though the GSTM1-null genotype was more common in laryngeal cancer subjects than in controls (55." (PMID 36013573, 2022).
leukopenia (4 papers, 2018 to 2024). "A comparison of GSTM1 null gene polymorphism in the group of children with leukopenia also found to be significantly decreased WBC (p = 0.0001), neutrophil (p = 0.0001), basophil (p = 0.0449), lymphocyte (p = 0.0001), and monocyte (p = 0.0014) counts." (PMID 30154939, 2018). "The authors found, in the univariate analysis, that GSTM1 wildtype genotype had a relationship with leukopenia and flue like symptoms, while GSTP1 variant was strongly associated with leukopenia." (PMID 30987408, 2019).
lung adenocarcinoma (4 papers, 2007 to 2022). A carcinoma that arises from the lung and is characterized by the presence of malignant glandular epithelial cells. "However, some studies gave the opposite results, where the deletion of GSTM1 was associated with an enhanced risk of non-small LC in Mongols and Chinese people, lung adenocarcinoma in North Indian residents and small-cell LC in South Indian inhabitants." (PMID 35207542, 2022). "Furthermore, a study in Caucasians reported a significant association between lung adenocarcinoma and the GSTM1 null genotype." (PMID 17897446, 2007).
lung disease (4 papers, 2007 to 2025). "Numerous studieshave demonstrated a significant association between subjectslacking GSTM1 activity and the risk of developing a formof lung disease." (PMID 17497028, 2007). "Another gene we identified, GSTM1 (gluthathione S-transferase μ 1, 1p13.3), belongs to a family of enzymes that are relevant for lung disease, likely through their roles in detoxifying electrophilic compounds, such as cigarette smoke and environmental toxins." (PMID 36698131, 2023).
Thrombocytopenia (4 papers, 2018 to 2024). A reduction in the number of circulating thrombocytes. "GSTM1-null and/or GSTT1-null genotypes are associated with the development of grades III–IV thrombocytopenia upon combined chemotherapy with rituximab and cyclophosphamide/doxorubicin/vincristine/prednisone or R-CHOP." (PMID 30914949, 2019).
acute kidney injury (3 papers, 2020 to 2024). Sudden and sustained deterioration of the kidney function characterized by decreased glomerular filtration rate, increased serum creatinine or oliguria. "It is reported that GSTM1 can repair acute kidney injury by reducing endoplasmic reticulum and oxidative stress." (PMID 36762111, 2023).
AIDS (3 papers, 2013 to 2025). A syndrome resulting from the acquired deficiency of cellular immunity caused by the human immunodeficiency virus (HIV). "Thus, it is suggested that HIV patients with GSTT1 and GSTM1 deletions are less susceptible to the progression of AIDS." (PMID 40867808, 2025). "Although deletion of GSTM1 has been identified as a risk factor for diseases of oxidative stress, and oxidative stress is implicated in the progression of HIV/AIDS, the effects of GSTM1 null allele polymorphism in HIV-infected populations are currently unknown." (PMID 24416632, 2013). "The study, to the best of our knowledge is the first to assess the association between homozygous deletion of GSTM1 and GSTT1 genes with HIV/AIDS disease progression in Ghanaian patients." (PMID 29795558, 2018). "This study sought to investigate the association between homozygous deletion of GSTM1 and GSTT1 genes (both null deletion) with HIV/AIDS disease progression in Ghanaian patients." (PMID 29795558, 2018). "In the current study, the association of GSTM1 and GSTT1 polymorphisms with oxidative stress among Ghanaian HIV/AIDS patients was studied." (PMID 29795558, 2018). "HIV/AIDS disease progression was assessed by measuring CD4+ cell count and viral load of the patients, and GST polymorphism was determined by amplifying the GSTT1 and GSTM1 genes using multiplex PCR, with CYP1A1 gene as an internal control." (PMID 29795558, 2018). "Human immunodeficiency virus (HIV) infection is associated with oxidative stress, but there is limited data on the frequency of deleted GSTM1 and GSTT1 genes in HIV/AIDS patients and their effect on progression among Ghanaians." (PMID 29795558, 2018).
asbestosis (3 papers, 2013 to 2025). A lung disorder caused by inhalation of asbestos fibers. "Asbestosis patients with Gstm1 deletion have a greater pleural scarring and higher risk of pulmonary parenchymal disease due to a gene-deletion-induced decrease in detoxification ability." (PMID 36615800, 2022). "Testing the interactions between different genotypes and smoking, GSTM1-null polymorphism was shown to modify the association between smoking and asbestosis, where an increased risk of asbestosis was found only among ever-smokers who had GSTM1-null genotype (OR = 1.48, P = 0.009)." (PMID 23984360, 2013). "Polymorphisms in glutathione S-transferase (GST) genes such as GSTM1 null, GSTT1 deletion, and high-activity GSTP1 genotypes have been associated with increased asbestosis risk, suggesting complex interactions in detoxification pathways." (PMID 41012395, 2025). "Nevertheless, this study demonstrates a strong interaction between GSTM1-null polymorphism and smoking, despite the fact that there was no independent association between either GSTM1-null polymorphism or smoking and asbestosis risk." (PMID 23984360, 2013). "The study comprised 262 cases with asbestosis and 265 controls with no asbestos-related disease previously studied for MnSOD, ECSOD, CAT, GSTT1, GSTM1, GSTP1, and iNOS polymorphisms." (PMID 23984360, 2013).
autism spectrum disorder (3 papers, 2016 to 2021). A spectrum of developmental disorders that includes autism, and Asperger syndrome. "The emphasis regarding GST polymorphisms in autism spectrum disorders has been put on GSTM1 and GSTT1 deletion polymorphisms, which, in carriers of GSTM1 null or GSTT1 null genotype, affect cell’s ability to metabolize toxins due to complete lack of active enzyme." (PMID 30824761, 2019). "We investigated interactive roles of three metabolic glutathione S-transferase (GST) genes (GSTP1, GSTT1, and GSTM1) and autism spectrum disorder (ASD) status in relation to blood Hg concentrations (BHC) of Jamaican children." (PMID 33546147, 2021).
brain inflammation (3 papers, 2022 to 2025). "Here we examined the mechanisms of how GSTM1 regulates astrocyte transcriptional program in response to pro-inflammatory signaling and further addressed the impact of GSTM1 loss-of-function on neurons during acute brain inflammation following a systemic injection of lipopolysaccharides (LPS)." (PMID 36685285, 2022). "The study demonstrated that astrocyte-specific knockdown of GSTM1 resulted in a significant reduction in microglial activation during LPS-induced brain inflammation." (PMID 40305200, 2025). "Our data revealed the broad influence of GSTM1 on the regulation of astrocyte transcriptional programs and implied the requirement of GSTM1 in the maintenance of neuronal activities during brain inflammation." (PMID 36685285, 2022). "Our data also revealed that GSTM1 reduction in astrocytes increased neuronal stress levels, attenuating neuronal activities during LPS-induced brain inflammation." (PMID 36685285, 2022). "We further showed that reduced GSTM1 expression in astrocytes impaired the neuronal activities and cellular stress in LPS-induced brain inflammation." (PMID 36685285, 2022). "We have recently discovered that GSTM1 promotes the production of pro-inflammatory mediators by astrocytes and enhances microglial activation during acute brain inflammation." (PMID 36685285, 2022). "For example, Gstm1, which is upregulated in HD microglia, is a glutathione S-transferase that contributes to astrocyte-mediated enhancement of microglia activation during brain inflammation." (PMID 38459557, 2024). "Here we report that GSTM1 significantly affects TNF-α-dependent transcriptional program in astrocytes and modulates neuronal activities and stress during brain inflammation." (PMID 36685285, 2022).
childhood asthma (3 papers, 2007 to 2019). "Prenatal TSE significantly increased the risk of childhood asthma in females with the GSTM1 null genotype (30.0% versus 9.4%, P = 0.001, OR: 4.107, 95% CI: 1.699–10.107) compared with the effect in the other 3 groups." (PMID 25328891, 2014). "In several studies, null alleles in the GSTT1 and GSTM1 genes (GSTT1*0 and GSTM1*0) were associated with childhood asthma but this finding was contradicted in other studies." (PMID 17497028, 2007).
Cognitive impairment (3 papers, 2013 to 2022). Abnormal cognition is characterized by deficits in thinking, reasoning, or remembering. "Therefore, further research is needed to determine the influence of APOE and GSTM1/T1 polymorphism on cognitive impairment among a larger random sample of Chinese elderly." (PMID 26404360, 2015). "However, the upregulation in the expression of hippocampal peroxiredoxin-5, isoform CRA_a and hippocampal glutathione S-transferase Mu 1 by matcha and decaffeinated matcha might show that these enzymes could be used as markers for the evaluation of aging and cognitive impairment." (PMID 35334854, 2022).
endometrial cancer (3 papers, 1997 to 2017). Primary or metastatic malignant neoplasm involving the endometrium (mucous membrane that lines the endometrial cavity). "A decreased risk of endometrial cancer was observed in women with a homozygous deletion of the GSTM1 gene when both SNP selected to represent the deletion were not called: HR: 0.80 (0.58–1.11)." (PMID 27713515, 2016). "In combination with the fact that we only observed an association between acrylamide and endometrial cancer risk in women with at least one copy of GSTM1, this could, in line with the results for the CYP2E1 SNPS, suggest that acrylamide itself is the causative compound in endometrial carcinogenesis." (PMID 27713515, 2016). "Previously, we investigated the interaction between genetic make-up and acrylamide intake for endometrial cancer risk, and we observed indications for interaction with SNPs in CYP2E1 and the deletions of GSTM1 and GSTT1." (PMID 28391539, 2017). "We observed that women with at least one copy of GSTM1 and GSTT1 were at an increased acrylamide-associated risk of endometrial cancer, which was contrary to what we expected." (PMID 27713515, 2016).
exfoliative glaucoma (3 papers, 2008 to 2013). "The aim of the present study was to investigate the association of glutathione S-transferase GSTT1 and GSTM1 genotypes with pseudoexfoliative glaucoma (PEXG) in a group of Pakistani patients." (PMID 21151336, 2010).
glioblastoma (3 papers, 2010 to 2022). The most malignant astrocytic tumor (WHO grade IV). "Although NF-kB signaling has been shown to promote gliomagenesis, the role of GSTM1 in enhancing NF-kB activity in glioblastoma remains to be determined." (PMID 34732244, 2021). "In conclusion, using ATAC-seq coupled with RNA-seq to analyze datasets from short-survival versus long-survival glioblastoma and tumor versus normal tissues, GSTM1 was shown to be a biomarker capable of predicting GBM patient survival." (PMID 34732244, 2021).
hemorrhagic cystitis (3 papers, 2017 to 2022). Inflammation of the bladder resulting in bloody urine. "The association observed with GSTM1 and hemorrhagic cystitis could derive from the interaction between busulfan and cyclophosphamide affecting the clearance of cyclophosphamide metabolites such as acrolein, which can be damaging to the kidney and bladder epithelium." (PMID 29207608, 2017). "Multivariate modelling for hemorrhagic cystitis included GSTM1, diagnosis, conditioning regimen and age, explaining 47% of variability of which 10% was attributed to GSTM1." (PMID 29207608, 2017). "Among other GST genes investigated, GSTP1 313GG correlated with acute graft versus host disease grade 1-4 (p=0.01) and GSTM1 non-null genotype was associated with hemorrhagic cystitis (p=0.003)." (PMID 29207608, 2017). "BU exposure was significantly associated with aGvHD, TRT and hemorrhagic cystitis and was further analyzed together with genotypes/diplotypes in a multivariate model in which both variables remained significant predictors of respective outcomes (GSTA1, p = 0.003, GSTM1, p = 0.005, Css p ≤ 0.05." (PMID 29207608, 2017). "Incidence of hemorrhagic cystitis was higher in GSTM1 non-null individuals compared to patients with GSTM1 deletion (p = 0.003)." (PMID 29207608, 2017).
metabolic syndrome (3 papers, 2013 to 2024). A cluster of metabolic risk factors for CARDIOVASCULAR DISEASES and TYPE 2 DIABETES MELLITUS. "Besides, in a controlled exposure study among individuals with metabolic syndrome, the GSTM1 null participants showed an increased QRS interval after acute exposure to concentrated ambient ultrafine particles." (PMID 30305173, 2018).
oesophageal cancer (3 papers, 2010 to 2021). "We have earlier reported a significant increase in the risk of oesophageal cancers correlated with the null genotypes of GSTM1 and GSTT1 but not with the GSTP1 Ile/Val polymorphism." (PMID 21134244, 2010). "The variation in the impact of GSTM1, GSTT1 and GSTP1 in oesophageal cancer susceptibility could be due to their differences in organ localization and metabolic functions." (PMID 20540773, 2010). "Genetic polymorphisms in genes involved in detoxification such as glutathione-S-transferases (GST), GSTM1, GSTT1 and GSTP1 could potentially affect the susceptibility of an individual to the adverse effects of environmental risk factors involved in oesophageal cancer." (PMID 21134244, 2010).
osteosarcoma (3 papers, 2013 to 2017). A usually aggressive malignant bone-forming mesenchymal neoplasm, predominantly affecting adolescents and young adults. "We further analyzed the role of GSTT1 and GSTM1 polymorphisms in the response to chemotherapy and survival of patients with osteosarcoma." (PMID 24353716, 2013). "The relationship of GSTM1, GSTT1 and GSTP1 gene polymorphisms with prognosis of osteosarcoma is shown in Table-III." (PMID 24353716, 2013). "Previous studies have indicated that variants of GSTT1 and GSTM1 did not associate with prognosis of osteosarcoma, which is in line with the results of our study." (PMID 24353716, 2013). "In previous studies, GSTM1 deletions have been linked to osteosarcoma incidence and recurrence, with a non-statistically significant positive association with soft tissue sarcoma mortality." (PMID 23637977, 2013).